CXCL1 (C-X-C motif chemokine ligand 1)
Diseases named in the same sentence as CXCL1 in open-access papers (continued):
Sharing a sentence is not in itself a finding about the gene and the disease.
asthma (47 papers, 2011 to 2025). "Neutrophilic inflammation, often associated with severe or steroid-resistant asthma, is driven by distinct pathways involving IL-8, GM-CSF, and chemokines like CXCL1 and CXCL5." (PMID 41259396, 2025). "Our findings revealed that the macrophage-derived Dectin-1/caspase-11/GSDMD pathway exhibited a pivotal pathogenic role in asthma via enhancing neutrophil migration through CXCL1/CXCL3/CXCL5-CXCR2 axis." (PMID 38459541, 2024). "CXCL1 is one of the most associated hub genes in the pathogenesis of severe asthma, which can be induced by IL-1β, IL-6 and so on." (PMID 38459541, 2024). "Many genes, including Il33, Cxcl5, Cxcl15, Ccl20, Cxcl3, Cxcl1, C3, and Pfn1, which have been linked to asthma pathogenesis, showed a cell type-specific response to HDM." (PMID 35627266, 2022). "CXCL-1, IL-5, IL-8, and IL-17A were positively associated with Difficult-to-Control asthma, while IL-4 and IL-13 were positively associated with Easy-to-Control asthma." (PMID 28686637, 2017). "CXCL1 is a hub gene with the one of the greatest number of associations in asthma which indicates that this chemokine may play an important role in this disease." (PMID 36613652, 2022). "Several other studies have shown that insufficient regulation of NF-κB signaling could be the origin of abnormally high expressions of IL-8 and CXCL1, which in turn may be the potential cause of neutrophilic infiltration in the lower airways of asthma patients." (PMID 31798831, 2019). "As previous studies have shown miR-146a capacity to suppress IL-8 and CXCL1 in other cell types, our results suggest that the lower expression of miR-146a may be linked to enhanced production of these chemokines by the airway epithelial cells in asthma." (PMID 31798831, 2019). "In this study, we found decreased levels of SCF and CXCL1 in asthma patients with positive IgE to Ascaris." (PMID 40943268, 2025). "Our study found that Dectin-1/caspase-11 activation in asthma is not only related to CXCL1, but also related to the secretion of CXCL3 and CXCL5." (PMID 38459541, 2024). "The top six upregulated DEG genes (IL6, CXCL8, TNF, DUSP2, ADM, and CXCL1) in SR asthma patients compared with SS asthma patients were identified." (PMID 37208441, 2023). "Collectively, these results indicated that elevated epithelial SIRT6 promoted IL-17A release, which induced MMPs and cytokines (eg, Mmp3, Mmp12, and Cxcl1) scretion in severe asthma." (PMID 38135684, 2023). "Seven hypermethylated (CCL11, TNF, IL5, CCL2, CXCL1, CCL8, IL17RB) mRNAs (>twofold compared with control) were finally selected, as their mRNAs have been clearly reported as being associated with asthma." (PMID 36250525, 2022). "In murine models of asthma, IL-17 stimulates and orchestrates airway neutrophilic infiltration by inducing the expression of neutrophil-attractant chemokines like CXCL1, CXCL2, IL-6, and IL-8 in humans." (PMID 35386663, 2022). "In asthmatics, there is a decrease in CXCL1 production by activated airway smooth muscle, which leads to the recruitment of mast cells that play an important role in the pathogenesis of asthma." (PMID 36613652, 2022). "CXCL1 expression in asthma depends on IL-17, an interleukin produced in asthmatics by eosinophils and T cells." (PMID 36613652, 2022). "It is able to also enhance production of neutrophil recruitment associated chemokines like CXCL8 (in humans), CXCL1, CXCL2, CXCL3, CXCL5, and IL-1b, particularly in mold allergen-induced asthma murine models." (PMID 35386663, 2022). "Several clinical trials have provided evidence implicating the CXCL1/CXCR2 axis as a therapeutic target for asthma, bronchiectasis, and cancer, with promising effects in chronic obstructive pulmonary disorder (COPD)." (PMID 33087182, 2020). "Taken together, we detected that airway epithelial cells from asthma patients with neutrophilic phenotype had expected increased expression of IL-8 and CXCL1 while asthmatics with eosinophilic phenotype had an enhanced expression of IL-33." (PMID 31798831, 2019).
asthma (continued). "Intratracheal administration of S. commune in OVA-induced asthma model mice enhanced neutrophilic airway inflammation, increased the mRNA expression of CXCL1 and CXCL2 in the lungs, and provoked IL-17A, and IL-17F production in BAL fluid." (PMID 31852931, 2019). "As the miR-146a level was reduced in the airway epithelial cells from patients with asthma, we next analyzed mRNA expression of miR-146a indirect (CXCL1 and IL-8) and direct (IRAK1) target genes in the same samples." (PMID 31798831, 2019). "For this purpose, we determined differential leukocyte counts and concentrations of IFN-γ, IL-5, IL-6, IL-13, and KC/CXCL1 in BALF in a mouse model of OVA-induced asthma." (PMID 29882826, 2018). "Previous analysis of airway secretion samples from predominantly African American children with asthma showed that, in addition to other cytokines and chemokines, Differential CXCL-1 and IL-8 concentrations characterized severe compared to moderate asthma." (PMID 28686637, 2017). "In this respect, to strengthen the notion that CXCL-1 plays an important role in asthma, a recent study have started the investigation of the potential clinical benefits of a selective CXCR2 receptor antagonist in patients with severe asthma." (PMID 25506835, 2014). "The decrease in CXCL1 in asthma leads to the increased recruitment of mast cells to the airways." (PMID 40943268, 2025). "In asthma, the phenotypic changes of macrophages, such as M1 polarization, can promote the pulmonary recruitment of neutrophils through the production of chemokines CXCL1." (PMID 38459541, 2024). "Therefore, our study suggested that Dectin-1/caspase-11-mediated macrophage pyroptosis promotes neutrophil airway infiltration in asthma, which depends on the secretion of chemokines such as CXCL1, CXCL3 and CXCL5." (PMID 38459541, 2024). "CXCL1 may also alleviate asthma symptoms as it inhibits the chemotaxis of mast cells, an effect dependent on CXCR2." (PMID 36613652, 2022). "The cause of the reduced miR-146a expression in asthmatic airways is not known, however, it may lead to the increased neutrophil-attracting chemokines IL-8 and CXCL1 and thereby contribute to the development of neutrophilic phenotype of asthma." (PMID 31798831, 2019). "Mahmutovic-Persson and colleagues demonstrated that airway polyI:C challenge in an allergic experimental asthma mouse model produced an exacerbation-like condition, with increased lung tissue inflammation and increased levels of neutrophils and CXCL1 expression in bronchoalveolar lavage (BAL)." (PMID 26418032, 2015). "Further work on the presence and role of CXCL1 (KC) in murine models of allergic inflammation may allow us to better understand the pathogenesis of disease and vascular remodeling during asthma." (PMID 22168152, 2011). "MiR-146a-5p has been also studied in chronic respiratory diseases such as asthma, a disease where wheezing is a key sign: this miRNA is found to be reduced in bronchial brushings from asthmatic individuals, and when over-expressed in epithelial cells, it reduces IL-8 and CXCL1." (PMID 36078154, 2022). "This was accompanied by reduced levels of CXCL1, CCL11, and CCL2 chemokines and the consequent reduced inflammation in lungs and airways which contributed to the improvement of pulmonary mechanics, the main cause of asthma complications and worsening of life quality of patients with asthma." (PMID 33123138, 2020). "Using a mouse (Mus musculus) model of asthma applied to the Collaborative Cross population, we previously identified a lung gene expression quantitative trait locus (eQTL) for Zinc finger protein 30 (Zfp30) that was also a QTL for neutrophil recruitment and the hallmark neutrophil chemokine CXCL1." (PMID 29242385, 2018). "The enhanced pulmonary CXCL1 production that we observed in myriocin‐treated lungs indicates that regulation of early responses to allergen may have an important upstream effect on asthma pathogenesis." (PMID 27621809, 2016).
asthma (continued). "CCL-3 and CCL-4 in serum and IgE, CXCL-1, GM-CSF, and IP-10 in nasal secretion may be considered as preferable biomarkers for predicting favorable or ineffective response to omalizumab therapy in patients with refractory CRSwNP comorbid with asthma, based on various clinical indicators." (PMID 39758936, 2025). "Gene transcripts of some of these chemokines (CXCL1, CXCL2, and CXCL5) were found to be upregulated in a mouse model of severe asthma." (PMID 36164329, 2022). "The IL-4/IL-13/STAT6 pathway induces expression of inflammatory chemokines such as CCL11, CXCL1, and CXCL3 and is a central pathway in the pathophysiology of asthma, especially airway hyperresponsiveness." (PMID 35281012, 2022). "While CXCL1, CXCL2, and CXCL5 gene transcripts were shown to be elevated in a mouse model of severe asthma, treatment with Ruxolitinib, an anti-inflammatory drug and powerful inhibitor of janus kinase 1/2 (JAK1/2), caused the upward spiraling to be reversed." (PMID 36164329, 2022). "Targeting of CXCL1 or its receptor CXCR2 with blocking antibodies was recently shown to reduce AHR and goblet cell metaplasia in a murine asthma model." (PMID 27621809, 2016). "They found that gene signature profiles of Th2 (IL-13, IL-4) and Th17 (CXCL1, CXCL2, CXCL3, IL-8, CSF3) immune responses were inversely correlated in these samples suggesting a reciprocal regulation of these two pathways in asthma." (PMID 26561853, 2015). "Other chemokines that appear to be induced by Alternaria are CXCL1 and CXCL6, potent neutrophil granulocyte chemoattractants that have been found in the early phase of experimental and clinical asthma and in the inflamed airway mucosa in COPD patients." (PMID 23882263, 2013). "In our study, we found ILC3s produced neutrophil chemoattractants including CXCL8, CXCL1, TNF-α and GM-CSF after IL-1β stimulation, suggesting ILC3s may mediate airway neutrophilia in asthma by release of neutrophil chemoattractants." (PMID 36949482, 2023). "In the present study, we demonstrated that tiotropium bromide improved bronchoconstriction, and that it significantly reduced the concentrations of IL-5, IL-6, IL-13, and KC/CXCL1 in BALF, and subsequently led to reduced neutrophilic airway inflammation in a mouse model of OVA-induced asthma." (PMID 29882826, 2018). "These specific genes, whose expression was attenuated by clarithromycin after IL-13 exposure, were dominantly categorized as “extracellular region,” “plasma membrane,” and “defense response” genes, among which asthma-related CD40, NOS2, and CXCL1 were included." (PMID 28219384, 2017). "Furthermore, a molecular phenotype characterized by the presence of CXCL1, RANTES, IFNγ, IL-12 and IL-10 separated children with severe asthma from those with moderate asthma." (PMID 22168152, 2011). "Another group showed that severe asthma was neither TH1 or TH2, but severe asthma was characterized by elevations in BAL CXCL1 (growth-related oncogene, GRO), RANTES (regulated on activation, normal T cell-expressed and -secreted, CCL5), IL-12, interferon (IFN)-γ and IL-10." (PMID 39596984, 2024). "Finally, intratracheally delivered PBS-PBS negative controls were also found to elicit ~40 pg/mL of CXCL-1 secretion, which is roughly equivalent to levels recorded in asthma patients (30 pg/mL)." (PMID 32605011, 2020). "Thus the addition of CXCL-1, IFN-γ, IL-5, IL-17A, EGF, eotaxin, IL-lβ, IL-4, IL-12p40, IL-13, and MDC serum concentrations to blood eosinophils and neutrophils adds significant value to the definition of the Difficult-to-Control asthma endotype." (PMID 28686637, 2017). "In this study, the expression of CXCL8 and CXCL1 in ILC3s upon IL-1β stimulation was insensitive to dexamethasone, suggesting that neutrophilic inflammation mediated by IL-1β-ILC3-CXCL8/CXCL1 axis may be involved in the development of steroid-resistant of asthma." (PMID 36949482, 2023).
asthma (continued). "Neutrophilic inflammation, CXCL-1 levels and pulmonary inflammation were not significantly different when comparing WT OVA+Sp and IL-22 KO OVA+Sp groups, suggesting that IL-22 is not involved in the comorbidity asthma and acute pneumonia that courses with neutrophilic inflammation." (PMID 37445595, 2023).
Obesity (46 papers, 2013 to 2026). Accumulation of substantial excess body fat. "Meanwhile, it was found that CXCL1 is required for obesity-associated adipose stromal cell recruitment, vascularization, and accelerated tumor growth." (PMID 41255573, 2025). "Previous studies have shown that an increase in serum CXCL1 is associated with obesity, hyperglycemia, and pancreatic dysfunction." (PMID 38558794, 2024). "New-onset postoperative obesity was associated with high expressions of CXCL1 (uOR = 3.67; 95% CI, 1.11–12.15; P = 0.034) and TNF (uOR = 2.92; 95% CI, 1.04–9.02; P = 0.045)." (PMID 38965454, 2024). "Increased CXCL-1 levels have been linked with obesity, hyperglycemia, and myocardial infarction in patients." (PMID 36675322, 2023). "Obesity is associated with chronic inflammation and high expression of CXCL1 in omental adipose tissue and blood." (PMID 35806156, 2022). "Adipose tissue in 25-week-old α7−/− mice had significantly higher expression of genes encoding for TNFα, IL-6, F4/80 and IL-15 as well as CXCL1, which are associated with obesity." (PMID 32708537, 2020). "As Cxcl1 is the cytokine that best correlates with anxiety-like behavior and has been previously associated with obesity, we injected lean animals with recombinant murine Cxcl1." (PMID 30612898, 2019). "Using murine cancer models, we demonstrate that the CXCL1 signalling through its receptors is rate-limiting for the obesity-associated ASC recruitment to tumours and their stimulatory effects on tumour vascularization and growth." (PMID 27241286, 2016). "Among those chemokines, Groα/CXCL1 was predicted to cause a 45% increase in obesity." (PMID 38541912, 2024). "It was recently described that adipose stromal cells can be recruited from white adipose tissue to tumor environments through CXCL1 signaling, suggesting that the increased aggressiveness of certain cancers is linked to white adipose tissue overgrowth in obesity." (PMID 29467755, 2018). "In addition, hepatic stellate cells were reported to exhibit senescence-associated secretory phenotype in mice with obesity, secreting various inflammatory and tumor-promoting factors in the liver, including IL-1β, IL-6 and CXCL1." (PMID 28458256, 2017). "Our results suggest that the obesity-associated CXCL1 expression by prostate epithelium could be responsible for recruitment of ASCs, the WAT stromal cells expressing CXCR1." (PMID 27241286, 2016). "Using a diet-induced obesity mouse model with breast cancer, researchers demonstrate that an elevated expression level of intratumor CXCL1 can induce the accumulation of CXCR2-expressing G-MDSC into the tumor microenvironment." (PMID 40863244, 2025). "Molecular investigation showed that CXCL1 triggered KEAP1 m6A demethylation via FTO (fat mass and obesity-associated protein) up-regulation, subsequently reducing NRF2 expression to exacerbate ROS burst and mitochondrial fission." (PMID 41255573, 2025). "However, using MR, we found that CXCL1 may reduce the risk of obesity." (PMID 38558794, 2024). "The secretion of multiple pro-inflammatory cytokines and chemokines (such as CXCL1) gives rise to the accumulation of M1 macrophages in adipose tissues, leading to insulin resistance and obesity." (PMID 39830328, 2024). "Relevant studies showed that CXCL10 and CXCL11 are potential predictive molecules for obesity onset and CXCL1 expression level is related to adipocyte differentiation." (PMID 37889664, 2023). "CXCR2 transfected OC cells expressed higher levels of CXCL1/2 compared to CXCR2 null OC cells and obesity-induced, higher circulating CXCL1 levels, indicating a positive feedback loop." (PMID 34638514, 2021). "Based on the high expression levels of CXCL1–3 and CXCL8 in OC cells and the high levels of CXCR2 in adipocytes, the CXCL1/8-CXCR2 axis is proposed as a molecular link between obesity and OC." (PMID 34638514, 2021).
Obesity (continued). "In fact, IL-6 is one of the primary mediators of low-grade inflammation in obesity and both CXCL-1 as well as IL-5 have been found to be altered in prediabetes." (PMID 32210914, 2020). "Concurrently, obesity increases intratumoral CXCL1 concentrations, promoting CXCR2-mediated accumulation of FasL+ G-MDSCs, resulting in heightened Fas/FasL-mediated CD8 TIL apoptosis and immunotherapy resistance." (PMID 33123173, 2020). "A mouse model of diet-induced obese (DIO) has suggested that obesity-induced secretion of CXCL1 by cancer cells creates a chemotactic gradient that enables ADSCs trafficking to tumors via CXCR1." (PMID 31861872, 2019). "First, hepatic neutrophil infiltration mediated by CXCL1 is a critical step for both liver damage and liver fibrosis in the synergistic effect of obesity and alcohol binge drinking." (PMID 29552626, 2018). "Obesity also augments O3-induced increases in BAL CXCL1 and CXCL2, and BAL concentrations of the type 2 cytokines, IL-13 and IL-5." (PMID 27472835, 2017). "Obesity also augmented ozone-induced increases in BAL CXCL1 and IL-6, and in BAL type 2 cytokines, whereas anti-ST2 treatment reduced these cytokines." (PMID 27472835, 2017). "Together, these results indicate that CXCL1 signalling via CXCR1 and CXCR2 mediates the obesity-associated stimulation of tumour growth." (PMID 27241286, 2016). "Future studies will establish a potential synergy and the relative clinical importance of CXCL1 and CXCL8 in obesity-linked and progressive disease." (PMID 27241286, 2016). "Using mouse models, we show that the CXCL1 chemokine gradient is required for the obesity-dependent tumour ASC recruitment, vascularization and tumour growth promotion." (PMID 27241286, 2016). "Serum levels of numerous obesity-linked chemokines promoting adipocyte proliferation (TIMP-1) and adipose macrophage infiltration (CXCL1, CXCL2, CXCL12, CCL3, and CCL5) were found to be significant predictors of in vivo hippocampal TSPO signals." (PMID 27578213, 2016). "Associated with these changes, obesity increased LFA-1 and ICAM-1 neutrophil expression and altered CXCL1 gradients." (PMID 26956558, 2016). "We also use the mouse model to demonstrate that blockade of either CXCL1 or its receptors inhibits obesity-dependent ASC tumour trafficking and abrogates the obesity-associated promotion of tumour vascularization and growth." (PMID 27241286, 2016). "Combined, our results suggest that in patients, CXCR1 expressed in ASCs in vivo, and possibly CXCR2, direct ASC trafficking towards CXCL8 gradient activated in cancer and CXCL1 gradient in addition activated in obesity." (PMID 27241286, 2016). "We also present the effects of obesity on CXCL1-related cancer processes." (PMID 41898553, 2026). "Higher expression levels of CXCL1 and CXCL8 were identified as independent risk factors for significant weight gain, and CXCL1 and TNF were identified as independent risk factors for new-onset postoperative obesity." (PMID 38965454, 2024). "Screening of obesity-associated proinflammatory cytokines and chemokines in subcutaneous white adipocytes demonstrated that BAFF, but not APRIL, upregulated the mRNA expression of multiple proinflammatory mediators, including Tnf, Cxcl1, Ccl2, and Ccl3." (PMID 34006859, 2021). "On the other hand, except for obesity, all other datasets showed upregulation of CXCL1." (PMID 34833079, 2021). "Thus, we have identified a pathway wherein obesity leads to increased intratumoral CXCL1 concentrations, which promotes CXCR2-mediated accumulation of FasL+ G-MDSCs, resulting in heightened CD8 TIL apoptosis and immunotherapy resistance." (PMID 33123173, 2020). "Importantly, CXCL1, S100A8, and NOD2 were also found to be positively associated with obesity in our murine study." (PMID 33123173, 2020).